LRPPRC (leucine rich pentatricopeptide repeat containing)
Diseases named in the same sentence as LRPPRC in open-access papers (continued):
Sharing a sentence is not in itself a finding about the gene and the disease.
tumor (continued). "Through functional approaches in in vitro and in vivo models it has been demonstrated that RPN11/PSMD14 supports tumor aggressive features through a mechanism that involves Leucine Rich Pentatricopeptide Repeat Containing (LRPPRC)." (PMID 39430244, 2024). "In contrast, LRPPRC knockdown resulted in significantly reduced growth and weight of subcutaneous xenograft tumours." (PMID 38372449, 2024). "Among tumor types, UCEC was found to present the most widespread somatic mutations of the disulfidptosis genes, such as SLC7A11 (92 %), NCKAP1 (85 %), LRPPRC (75 %), and OXSM (75 %)." (PMID 39605832, 2024). "Meanwhile, we found that the expression of WDR76, as a tumour suppressor, was significantly reduced upon LRPPRC knockdown among 68 candidate genes screened." (PMID 38372449, 2024). "More importantly, LRPPRC knockdown attenuated glycolysis and inhibited tumour growth while increasing the cellular consumption of glutamine in TNBC." (PMID 38372449, 2024). "Meanwhile, using metabolomic methods, metabolite detection and cell phenotype assays, we demonstrated that LRPPRC enhanced glycolysis, thereby promoting tumour progression both in vivo and in vitro." (PMID 38372449, 2024). "More specifically, 61% of tumor tissues (192 of 317) were LRPPRC positive, which was significantly higher than that in benign ovarian cysts (14%, 11 of 79)." (PMID 37496051, 2023). "Leucine-rich pentatricopeptide repeat-containing protein (LRPPRC) has recently emerged as a novel N6-methyladenosine (m6A) modification reader with potential implications for tumor progression." (PMID 37892851, 2023). "Considering the overexpression of LRPPRC in multiple tumor types, our drug combination strategy has the potential to be effective in various solid tumors." (PMID 37452037, 2023). "To conclude, our study posits that DRGs, especially MYH9 and LRPPRC, hold potential as pivotal architects of the tumor immune milieu in OS." (PMID 37892851, 2023). "Prior investigations underscored that inhibiting LRPPRC activity curtailed tumor expansion in murine models." (PMID 37892851, 2023). "Transplantation of A2780 cells with stable shRNA-mediated knockdown of LRPPRC in our mouse model also led to remarkable inhibition of tumorigenicity, with an average suppression rate of 43.9% according to tumor volume." (PMID 37496051, 2023). "Overexpressed LRPPRC negatively correlated with the overall survival of OC, representing a new OC tumor marker." (PMID 37496051, 2023). "In the suspension culture system, LRPPRC knockdown significantly decreased the number of tumor spheres, and the diameter of tumor spheroids was decreased by nearly 50% after LRPPRC knockdown." (PMID 37496051, 2023). "The posttranscriptional mechanism of LRPPRC on PD-L1 and anti-tumor immunity was elucidated in HCC cells via RIP, MeRIP−qPCR, RNA stability, immunohistochemical staining, and so forth." (PMID 37063837, 2023). "Altogether, our work on LRPPRC-mediated m6A modification of PD-L1 mRNA and anti-tumor immunity offered a new mechanism for m6A regulator-mediated immunosuppression in HCC." (PMID 37063837, 2023). "Knockdown of LRPPRC inhibited the proliferation of OC cells and led to a depletion of tumor stem cells in vitro and reduced subcutaneous tumorigenesis in vivo." (PMID 37496051, 2023). "Tumor tissues from CDK4/6i monotherapy showed higher protein levels of LRPPRC and CDK6 compared to the control group, indicating the activation of the LRPPRC-CDK6 feedback loop after CDK4/6i treatment in vivo." (PMID 37452037, 2023). "LRPPRC gene silencing significantly inhibited the growth and invasion of tumor cells, induced apoptosis, and reduced their drug resistance." (PMID 37399661, 2023). "In the in vivo subcutaneous tumors model, ribociclib significantly reduced the tumor formation rate and average tumor volume of LRPPRC+/- cells, and the anti-tumor effect was much better than that with control cell-generated subcutaneous tumors." (PMID 37452037, 2023).
tumor (continued). "Conversely, high levels of the mitochondrial-associated protein LRPPRC inhibit autophagy, and in Y79 and WERI-Rb-1 cells, high levels of LRPPRC activate ROS production and promote tumor progression." (PMID 36338723, 2022). "Our study discloses the novel functions of LRPPRC and explores new mechanisms responsible for the tumor-promoting effect of LRPPRC." (PMID 34671012, 2021). "In TCGA cohort, the expression levels of LRPPRC and RBM15B and the m6A risk score were significantly correlated with tumour grade and T stage." (PMID 34512165, 2021). "Since the expression levels of the four selected genes (KIAA1429, LRPPRC, RBM15B, and YTHDF2) play a crucial role in tumorigenesis and tumour development, we employed them to establish an m6A risk signature model." (PMID 34512165, 2021). "In the ICGC cohort, KIAA1429, LRPPRC, RBM15B, and YTHDF2 expression levels and the m6A risk score were significantly correlated with tumour grade." (PMID 34512165, 2021). "Downregulation of LRPPRC inhibits growth and invasion, induces apoptosis, and overcomes drug resistance in tumor cells." (PMID 31178748, 2019). "To understand the role of LRPPRC in tumor development, previously we reported that LRPPRC forms a ternary complex with Beclin 1 and Bcl-2 to inhibit autophagy." (PMID 24722279, 2014). "As T-96 directly bound to LRPPRC, we performed transcriptome analyses of A549 cells to determine whether T-96 affects the oxidative phosphorylation pathway in tumor cells." (PMID 39744573, 2025). "Similarly, overexpression of LRPPRC resulted in an obvious increase in the growth and weight of subcutaneous xenograft tumours, and this effect was attenuated by FX‐11." (PMID 38372449, 2024). "LRPPRC expression showed a positive correlation with Th2 cells and a negative correlation with NK CD56bright cells, which may accelerate tumor progression." (PMID 37534256, 2023). "The colony-forming assays showed this combination harbored significantly better anti-tumor activity than the single drug, indicating the LRPPRC-mediated OXPHOS could also promote CDK4/6i resistance in LUAD." (PMID 37452037, 2023). "Moreover, LRPPRC suppression mitigated tumor growth in murine models and improved anti-tumor immunity and immune infiltration in tumors." (PMID 37063837, 2023). "Therefore, in vivo, experiments demonstrated that targeting LRPPRC protein by GAA can achieve tumor cell-specific oxidative phosphorylation inhibition." (PMID 37496051, 2023). "Moreover, SNHG17 enhances the stability of c-Myc protein by directly binding to LRPPRC and, in turn, promotes G1/S transition and tumor growth." (PMID 34671012, 2021). "However, unpaired T-tests results showed that RBMX and LRPPRC were significantly up-regulated in tumor tissues compared with normal tissues." (PMID 34149792, 2021). "Additionally, KIAA1429, LRPPRC, and RBM15B and the m6A risk scores were significantly different between different tumour stages." (PMID 34512165, 2021). "The role of LRPPRC in tumor development remains inconclusive." (PMID 34671012, 2021). "Knockdown of LRPPRC promotes apoptosis and reduces tumor invasiveness." (PMID 27799870, 2016). "This may also provide a basis for the tumor-associated elevation in EPRS, which was positively correlated with LRPPRC and COPG1." (PMID 27799870, 2016). "However, when overexpressed, the LRPPRC acts as a tumor oncogene." (PMID 40563592, 2025). "Previous studies have demonstrated that LRPPRC, a member of the pentatricopeptide repeat (PPR) family, is an RNA‐binding protein that regulates cellular growth, invasion, apoptosis and drug resistance, is highly expressed in various tumours and is associated with unfavourable prognosis." (PMID 38372449, 2024).
tumor (continued). "Thus, it was hypothesized that LRPPRC expression may affect the response to immunotherapy by inhibiting the infiltration and activation of immune cells in the tumor microenvironment, and acts as a potential immunotherapy marker." (PMID 39199429, 2024). "In addition, tumor growth was notably slowed down by LRPPRC knockdown." (PMID 37063837, 2023). "Under the DNA methylation and gene silencing, Hypermethylation of tumour suppressor genes such as DAPK1, LRPPRC, and ZNF471 were reported." (PMID 41487403, 2026). "Since shikonin effectively eliminates SDHA-overexpressing tumor cells while targeting LRPPRC, this suggests a potential unexplored interaction or dependence between SDHA and LRPPRC proteins." (PMID 40563592, 2025). "ELISA, western blot, and xenograft tumor experiments were implemented to confirm the impact of LARS and the LRPPRC/HIF-1α axis on malignant progression and glycolysis." (PMID 40775462, 2025). "LRPPRC, a member of the PPR family that plays important roles in RNA stability, splicing and editing, has been shown to be dysregulated during tumour progression." (PMID 38372449, 2024). "The influence of LRPPRC on malignant behaviors of HCC cells was investigated through in vitro assays and xenograft tumor murine models." (PMID 37063837, 2023). "We analyzed the expression of genes in tumor and normal samples, and the results showed that NDUFS1, NDUFS2, NDUFC1, and EPAS1 were downregulated in CRC, and SLC7A11, OXSM, LRPPRC, NDIFA11, NUBPL, and CONT1 were upregulated in CRC." (PMID 37978247, 2023). "After further screening, we evaluated the relationship between expression of FMR1, LRPPRC, RBMX, YTHDC2, IGF2BP1 and clinical parameters, including stage, T (tumor infiltrating), N (lymphatic metastasis) and M (distant metastasis) in CRC." (PMID 37194014, 2023). "We evaluated the relationship between expression patterns of RBMX, FMR1, LRPPRC, YTHDC2, IGF2BP1 and clinical parameters, including stage, T (tumor infiltration), N (lymphatic metastasis), M (distant metastasis) in CRC." (PMID 37194014, 2023). "Thus, LRPPRC downregulation may mitigate tumor growth in HCC." (PMID 37063837, 2023). "The combination of high expression of LRPPRC and low expression of MAP1S can inhibit autophagy and promote tumor development." (PMID 34745261, 2021). "Our data show that seven m6A regulators (CBLL1, ELAVL1, LRPPRC, RBM15B, YTHDF1, YTHDF2, and ZC3H13) are related to tumorigenesis, tumor microenvironment and tumor prognosis." (PMID 33670062, 2021). "It appeared that IGF2BP1/3, ELAVL1, HNRNPA2B1, HNRNPC, KIAA1429, RBM15, LRPPRC, FMR1, YTHDF1/2 are highly expressed in the tumor while FTO, METTL14/16, WTAP, YTHDC1 and ZC3H13 are down-regulated." (PMID 35095993, 2021). "Genes like DAPK1, LRPPRC, RAB6C, and ZNF471 are found to be the targets of promoter hypermethylation that leads to the altered gene expression patterns that help in growth of tumours." (PMID 41487403, 2026). "Similarly, the expression of a few regulators is affected by the patients’ tumor grade, in cancers such as HNSC, KIRC, LGG, LIHC, PAAD, and UCEC; LRPPRC and TRMT112 are affected by tumor grade in most of the cancers." (PMID 39457524, 2024). "Collectively, our study provides a new strategy for the treatment of LRPPRC+ TNBC and may expand the application of drugs that target tumour metabolism in TNBC." (PMID 38372449, 2024). "The expression of the regulators significantly varies based on tumor stage in a few cancers, including KIRP, KIRC, KICH, LIHC, OV, THCA, and TGCT; IGF2BP2 in KIRC and THCA; IGF2BP3 in KIRP, KIRC, and UCEC; and LRPPRC and METTL14 in KIRC are the ones that are the most varied." (PMID 39457524, 2024). "Additionally, the expression of most of the regulators influences the tumor T feature of KIRC, LIHC, PRAD, STAD and THCA, especially IGF2BP1 in BRCA; IGF2BP2, IGF2BP3, LRPPRC, and METTL14 in KIRC; and IGF2BP3 in KIRP." (PMID 39457524, 2024).
tumor (continued). "LRPPRC is overexpressed in TNBC, enhancing glycolysis and promoting tumour progression." (PMID 38372449, 2024). "After treatment with GAA, a robust anti-tumor function was shown in the LRPPRC-positive LUAD-PDX models but not in the LRPPRC-negative PDX models." (PMID 37035154, 2023). "Therefore, LRPPRC promoted the new mitochondrial OXPHOS synthesis, which is essential for tumor stem cell maintenance and in vivo tumorigenesis." (PMID 37496051, 2023). "This work reveals a function of both LRPPRC and CDK6 in tumor development and CDK4/6i resistance." (PMID 37452037, 2023). "LRPPRC presents a negative correlation to most tumor-infiltrating immune cells in lung adenocarcinoma." (PMID 37063837, 2023). "Moreover, LRPPRC exhibited the highest expression in cluster 5 tumor cells, which displayed pronounced epithelial-mesenchymal transition (EMT) characteristics, suggesting that LRPPRC may play a role in promoting tumor migration and invasion." (PMID 39445012, 2024). "However, the tumor tissues in the GAA treatment group and the combination group showed lower levels of LRPPRC and CDK6 than the control group and CDK4/6i monotherapy group, suggesting that the addition of GAA can also block the LRPPRC-CDK6 feedback loop in vivo." (PMID 37452037, 2023). "Collectively, this work uncovered the m6A modification role of LRPPRC in PD-L1 mRNA stabilization in HCC cells and broadened the knowledge of a novel posttranscriptional regulation mechanism of PD-L1 expression and the functional significance of LRPPRC in anti-tumor immunity." (PMID 37063837, 2023). "The results showed that increased expression of LRPPRC was significantly correlated with the depth of tumor infiltration (T stage, P < 0.001, N stage P < 0.001 and M stage P = 0.002), whereas not with age, gender, tumor locus, tumor grade and TNM stage." (PMID 24375316, 2014). "However, the roles of LRPPRC in regulating OXPHOS and tumor progression in OC remain unknown." (PMID 37496051, 2023).
cancer (54 papers, 2014 to 2026). A tumor composed of atypical neoplastic, often pleomorphic cells that invade other tissues. "LRPPRC is implicated in driving cancer progression by integrating signals from upstream regulators, engaging with interaction partners, and modulating downstream targets." (PMID 40563592, 2025). "For instance, mitophagy can act as a tumor-suppressive mechanism (as suggested by the association between its inhibitor LRPPRC and poor prognosis), yet it also serves as a survival mechanism for cancer cells under stress." (PMID 41282600, 2025). "CDKN2A displayed higher mutation rates across multiple cancer types (31%), and other frequently mutated genes included LRPPRC (13%), PRKAA2 (11%), VLDLR (9%), ASNS (8%), GZMA (7%), GLS (7%), TNFRSF1A (6%), PSAT1 (5%), and PRDX6 (4%)." (PMID 37534256, 2023). "Similar to the results of SNHG17, LRPPRC was upregulated in different types of cancer and high LRPPRC level was associated with worse survival of HCC patients." (PMID 34671012, 2021). "To better understand the role of LRPPRC in cancer development, we have previously reported that LRPPRC associates with mitochondria, interacts with Beclin 1 and Bcl-2 and form a ternary complex to maintain the Bcl-2 stability." (PMID 24722279, 2014). "Indeed, LRPPRC is overexpressed in various human tumors, which is associated with poor prognosis, and downregulation of LRPPRC suppresses oncogenic activity, triggers apoptosis, and overcomes drug resistance in cancer cells." (PMID 38377789, 2024). "Additionally, aspirin treatment also significantly decreased the expression of genes encoding cytoskeleton including ARPC5, NEXN and LRPPRC, which may be helpful to understand the mechanisms behind aspirin suppressing the metastasis of cancer cells." (PMID 28184026, 2017). "The synergistic effects of the candidate compound were validated in multiple cancer cell lines with either genetic ablation or pharmacological inhibition of LRPPRC." (PMID 41901318, 2026). "The inhibition of LRPPRC by shikonin in those cell lines significantly suppressed mitochondrial respiration, leading to bioenergetic dysfunction and cancer cell death." (PMID 40563592, 2025). "Elevated levels of mitophagy inhibitor LRPPRC are positively correlated with poor prognosis and shorter survival in PC patients, suggesting an anti-cancer effect of mitophagy." (PMID 41282600, 2025). "In conclusion, LRPPRC, a scarcely studied protein in cancer research, was found to have a connection to worse survival rates among UCEC patients." (PMID 39445012, 2024). "The disulfidptosis genes: NCKAP1, LRPPRC, SLC7A11, OXSM, SLC3A2, NDUFS1, and GYS1 occurred somatic mutations in pan-cancer, with 1 % SNV frequency." (PMID 39605832, 2024). "Consistently, DepMap analysis revealed a strong correlation in gene effect between METTL17 and LRPPRC, MRPS9, MRPS22, and MRPS35, highlighting the significance of METTL17-associated cellular functions in cancer cell survival and ferroptosis defense." (PMID 38377789, 2024). "(d) LRPPRC (Leucine Rich Pentatricopeptide Repeat Containing) has multiple functions that can influence cancer." (PMID 39715885, 2024). "As we have demonstrated that the use of LRPPRC-specific inhibitor, GAA, reduces CDK6 expression, we offer a approach for therapy against cancer stem cells by targeting LRPPRC." (PMID 37452037, 2023). "Further immunohistochemistry showed that SLC7A11 and LRPPRC were higher in cancer tissues than in normal tissues." (PMID 37399661, 2023). "Our study reveals a mechanism responsible for CDK4/6i resistance and provides an enlightening approach to investigating the combinations of CDK4/6 and LRPPRC inhibitors in cancer therapy." (PMID 37452037, 2023). "The increases in the various cell lines and the cancer tissues of the LRPPRC expression were illustrated by the earlier studies too." (PMID 34745261, 2021).